BECN1 (beclin 1)
Diseases named in the same sentence as BECN1 in open-access papers (continued):
Sharing a sentence is not in itself a finding about the gene and the disease.
acute pancreatitis (2 papers, 2022). An acute inflammatory process that leads to necrosis of the pancreatic parenchyma. "Hu et al7 demonstrated that PVT1 promotes the development of acute pancreatitis by inducing autophagy activation of pancreatic acinar cells by regulating mir-30A-5p/Beclin-1 axis." (PMID 35723715, 2022). "In addition, the lncRNA-PVT1/miR-30a-5p/Beclin-1 axis is a potential target to improve severe acute pancreatitis." (PMID 35410457, 2022).
adenoma (2 papers, 2014 to 2020). A neoplasm arising from the epithelium. "During the adenoma-carcinoma sequence, we found Atg7 to be upregulated and Beclin-1 to be downregulated, while LC3b and the scaffold protein p62 stayed unaffected." (PMID 32046105, 2020). "According to the ISH data, Beclin 1 expression was lower in colorectal non-neoplastic mucosa (NNM) than adenoma and carcinoma (p < 0.05)." (PMID 25196438, 2014).
age (2 papers, 2023 to 2025). A temporal measurement of the time period elapsed since an identifiable point in the life cycle of an organism. "ATG6, ATG9, and Beclin-1 are some of the cellular components that can lose their function due to age-related paralysis." (PMID 37662706, 2023).
amyotrophic lateral sclerosis (2 papers, 2015 to 2023). Amyotrophic lateral sclerosis (ALS) is a neurodegenerative disease characterized by progressive muscular paralysis reflecting degeneration of motor neurons in the primary motor cortex, corticospinal tracts, brainstem and spinal cord. "Downregulation of the IRE1α-XBP1 axis in Huntington’s disease and amyotrophic lateral sclerosis induces autophagy by upregulating the forkhead box (FOXO), which is known to elevate key autophagy-related genes such as ATG12, BECN1, BNIP3, GABARAPL1, and LC3, and promote pathological conditions." (PMID 36860271, 2023).
Arthritis (2 papers, 2022 to 2025). Inflammation of a joint. "In our study, the administration of CFA dramatically lowered the articular gene expression of ULK-1, Beclin-1, and ATG-7 as compared to control rats, leading to significant downregulation in the autophagy process, supporting the hypothesis of autophagy involvement in hindering arthritis severity." (PMID 40350466, 2025).
Atrophy (2 papers, 2022 to 2023). Any weakening or degeneration, especially through lack of use. "The expression levels of NF-κB and Beclin 1 were significantly increased in the treatment group in comparison with the atrophy group (p < 0.01)." (PMID 37895907, 2023).
B-cell acute lymphoblastic leukemia (2 papers, 2022 to 2024). A neoplasm of lymphoblasts committed to the B-cell lineage, typically composed of small to medium-sized blast cells. "A transcript variant of the BECN1 gene carrying a deletion of exon 11, BECN1S, which encodes a C-terminal truncated BECN1 splice isoform, is reported in human B-cell acute lymphoblastic leukemia cells." (PMID 35585060, 2022).
benign prostatic hyperplasia (2 papers, 2015 to 2022). A non-cancerous nodular enlargement of the prostate gland. "This study aims to explore the effect of silencing Beclin-1 gene on autophagy and apoptosis of Benign Prostatic Hyperplasia (BPH) (BPH-1) cells under the condition of Androgen Deprivation (AD) and Autophagy Inhibition (AI)." (PMID 36088885, 2022). "Moreover, a number of Atg genes, such as Beclin 1 and LC3 genes, map to chromosomal loci that are frequently monoallelically deleted in PCa cells and the protein expression of Beclin 1 ad LC3 have been demonstrated to be lower in prostate adenocarcinoma than in prostate benign hyperplasia." (PMID 25821782, 2015).
breast adenocarcinoma (2 papers, 2015 to 2024). "Human breast adenocarcinoma MCF7 cells express low levels of endogenous Beclin 1 and we stably transfected Vector control, Beclin 1 WT or the 2KR mutant into MCF7 cells." (PMID 26008601, 2015).
cardiac arrest (2 papers, 2022 to 2024). Cessation of breathing and/or cardiac function. "Autophagy (BECN1) gene expression in the CA1 area of the hippocampus after cardiac arrest with survival at 2, 7, and 30 days was within control limits." (PMID 38279289, 2024). "BECN1 gene expression in the temporal cortex 2 days after cardiac arrest was above the control value, while after 7 and 30 days it oscillated around control values." (PMID 38279289, 2024). "BECN1 gene expression in CA3 increased significantly on day 30 after cardiac arrest." (PMID 38279289, 2024).
cerebral toxoplasmosis (2 papers, 2010 to 2025). Infections of the brain caused by the protozoan toxoplasma gondii that primarily arise in individuals with immunologic deficiency syndromes (see also aids-related opportunistic infections). "Based on these findings, we hypothesized that mice with a partial defect in Beclin 1 would exhibit impaired killing of T. gondii and susceptibility to ocular and cerebral toxoplasmosis." (PMID 21217818, 2010).
cervical squamous cell carcinoma (2 papers, 2015 to 2025). A squamous cell carcinoma arising from the cervical epithelium. "Loss of the BECN1 gene, which encodes Beclin 1, essential for phagophore formation, has been observed in breast, prostate, ovarian, hepatocellular, and cervical squamous-cell carcinomas." (PMID 40806457, 2025).
chondrosarcoma (2 papers, 2013 to 2022). A malignant cartilaginous matrix-producing mesenchymal neoplasm arising from the bone and soft tissue. "HIF-2α and Beclin 1 had a significant inverse relationship with the prognosis in patients with chondrosarcoma." (PMID 35163019, 2022). "In this study, the level of Beclin 1, a key mediator of autophagy, was significantly more decreased in chondrosarcoma tissues compared to normal tissues." (PMID 35163019, 2022).
chronic viral hepatitis (2 papers, 2012 to 2021). "High Beclin 1, Bcl-xL and Bad levels in CH and CIRR tissues suggest an interaction between autophagy and apoptosis in the early and intermediate stages of viral hepatitis." (PMID 22928777, 2012). "Also, Al-Shenawy (2016), had found that Beclin-1 revealed negative expression in HCC cases while over-expressed in liver tissues of chronic viral hepatitis." (PMID 33906303, 2021).
Co-infection (2 papers, 2016 to 2017). "Co-infection with α-syn and miR-101 induced a significant decrease in Beclin 1 and LC3 protein levels, and a significant increase in p62 in CG-4 cells when compared to the control condition, worsening the effects of α-syn alone." (PMID 29089869, 2017).
colon adenocarcinoma (2 papers, 2016 to 2022). "Therefore, the protein levels of autophagic markers BECN1 and LC3 are overexpressed in selected colon adenocarcinoma cell lines." (PMID 26802026, 2016).
degenerative disc diseases (2 papers, 2017 to 2022). "In this study, we found that changes in miR-129-5P and Beclin-1 levels and autophagic activity were associated with disc degeneration." (PMID 29156793, 2017).
dementia (2 papers, 2022 to 2025). Loss of intellectual abilities interfering with an individual's social and occupational functions. "As TKIs effectively lead to amyloid clearance by ubiquitination of Parkin and activation of Parkin–beclin-1 interaction, the prescription of TKIs may be associated with a lower risk of dementia and PD." (PMID 40937178, 2025).
encephalomyelitis (2 papers, 2017 to 2022). Inflammation of the brain and the spinal cord. "T cell-specific deletion of beclin 1 (Atg6) in mice fails to induce T cell-dependent humoral immune responses and resistance to encephalomyelitis." (PMID 28895911, 2017).
endometrioid adenocarcinoma (2 papers, 2014 to 2023). An adenocarcinoma characterized by the presence of malignant glandular epithelial cells resembling endometrial cells. "Increased expression of BECLIN 1 was found also to be associated with the most aggressive endometrioid adenocarcinomas and poor 5-year overall survival, probably because of concomitant tumour hypoxia." (PMID 25136588, 2014). "More in detail, >20% BECLIN 1-positive cells (>40 H) were found in the majority of endometrioid adenocarcinomas (11/13) and of serous cystadenocarcinomas (19/27)." (PMID 25136588, 2014).
Erythema (2 papers, 2023 to 2024). Redness of the skin, caused by hyperemia of the capillaries in the lower layers of the skin. "Our study also revealed a significant correlation between the increase in skin Beclin-1 levels, triggered by a 12-week application of the facial serum, and a decrease in both the melanin and erythema indexes." (PMID 38130575, 2023). "These associations suggest that an increased expression of Beclin-1 is linked to an increase in skin hydration and a decrease in TEWL, melanin index, and erythema index." (PMID 38130575, 2023). "Specifically, our findings indicate that the application of the serum leads to an upregulation of Beclin-1 expression, resulting in improved skin hydration and decreased TEWL, melanin index, and erythema index." (PMID 38130575, 2023).
focal segmental glomerulosclerosis (2 papers, 2017 to 2019). A renal disorder characterized by sclerotic lesions in the glomeruli. "Podocytes from patients with minimal change disease (MCD) showed higher levels of Beclin 1-mediated autophagic activity than those from patients with focal segmental glomerulosclerosis (FSGS)." (PMID 31815154, 2019).
glomerulosclerosis (2 papers, 2019 to 2022). A hardening of the kidney glomerulus caused by scarring of the blood vessels. "In contrast, we report the rapid development of proteinuria and glomerulosclerosis in Becn1 deficiency, clearly indicating a broad role played by BECLIN1 that encompasses more than autophagy pathway activation." (PMID 35409185, 2022). "Phenotypically, podocyte-specific deletion of Becn1 resulted in early-onset glomerulosclerosis, which rapidly progressed and dramatically reduced mouse life span." (PMID 35409185, 2022).
gynecological cancers (2 papers, 2014 to 2019). "In accordance with our results, AKT downregulation has already reported as being involved in autophagy and apoptosis through the beclin-1 block, and the PI3K/AKT/mTOR pathway has been implicated as one of the principals of autophagy pathways in gynecological cancers." (PMID 31683835, 2019). "We have studied the biological and clinical significance of BECLIN 1 and LC3 in ovary tumours of different histological types." (PMID 25136588, 2014).
Hyperammonemia (2 papers, 2017 to 2021). An increased concentration of ammonia in the blood. "Studies in mice with constitutive activation of autophagy unravelled Beclin‐1 as druggable candidate for therapy of hyperammonemia." (PMID 33369168, 2021). "In conclusion, this study shows a key role of liver autophagy in nitrogen homeostasis and indicates that Beclin‐1 as a druggable target for therapy of hyperammonemia and UCD." (PMID 33369168, 2021). "Therefore, consistent with previous findings, gain‐of‐function mutation of the autophagy activator Becn1 protects against acute hyperammonemia in vivo, suggesting that Beclin‐1 is a druggable candidate for therapy of hyperammonemia." (PMID 33369168, 2021).
Hypopharyngeal Squamous Cell Carcinoma (2 papers, 2013 to 2016). "Beclin-1 was positively expressed in 42.7% (35/82) of the hypopharyngeal squamous cell carcinoma specimens, which was markedly lower than that of adjacent non-cancerous tissues (79.6%, 43/54) (P<0.0001)." (PMID 23935917, 2013). "In other cancers, such as human hypopharyngeal squamous cell carcinoma (HSCC), expression of Beclin 1 and LC3II correlates with poor prognosis." (PMID 27846885, 2016). "Beclin-1 and LC3 were observed mainly in the cytoplasms or cytomembranes of hypopharyngeal squamous cell carcinoma cells and adjacent normal squamous epithelial cells." (PMID 23935917, 2013). "This study was designed to investigate the expression of beclin-1 and LC3 and to clarify their clinical significance in hypopharyngeal squamous cell carcinoma (HSCC)." (PMID 23935917, 2013). "We hypothesized that beclin-1 and LC3 are aberrantly expressed in hypopharyngeal squamous cell carcinomas." (PMID 23935917, 2013). "Expression patterns of beclin-1 and LC3 in hypopharyngeal squamous cell carcinoma (HSCC) and adjacent non-tumor tissues." (PMID 23935917, 2013). "We demonstrated that the expression of both beclin-1 and LC3-II are significantly lower in hypopharyngeal squamous cell carcinoma tissues than in adjacent non-cancerous tissues." (PMID 23935917, 2013). "However, the expression of beclin-1 and LC3 has not been characterized in hypopharyngeal squamous cell carcinoma." (PMID 23935917, 2013).
hypoxic-ischemic encephalopathy (2 papers, 2024). "In a neonatal hypoxic-ischemic encephalopathy model, intraperitoneal injection of MT (15 mg/kg) into pups 1 h before hypoxia induction upregulated the expression of NLRX1, which downregulated mTOR expression and promoted ATG7 and Beclin-1 expression to promote mitophagy and inhibit apoptosis." (PMID 38786094, 2024).
influenza (2 papers, 2011 to 2024). An acute viral infection of the respiratory tract, occurring in isolated cases, in epidemics, or in pandemics; it is caused by serologically different strains of viruses (influenzaviruses) designated A, B, and C, has a 3-day incubation period, and usually lasts for 3 to 10 days. "The drug further stimulates microtubule-associated protein 1 light chain 3 (LC3) and Beclin-1 (BECN1) genes, essential for autophagy processes that help degrade intracellular influenza particles." (PMID 39772244, 2024).
invasive carcinoma (2 papers, 2013 to 2015). A carcinoma that is not confined to the epithelium, and has spread to the surrounding stroma. "Immunoreactivity of the anti-beclin-1 antibody was observed in the cancer cells of 68 of 115 tissue specimens and in the mesenchymal stromal cells of 38 of 115 invasive carcinoma tissue specimens." (PMID 25955408, 2015).
keloid (2 papers, 2019 to 2020). An irregularly shaped, elevated mark on the skin caused by deposits of excessive amounts of collagen during wound healing. "To assess the consequences of glycyrrhizin-induced autophagy in keloids, we examined the changes in Beclin 1 expression and the conversion rate of LC3-I to LC3-II in KFs." (PMID 31450620, 2019). "Beclin 1 and LC3 expressions were significantly reduced in keloid tissues treated with glycyrrhizin by 18.1% and 24.6%, respectively (*** p < 0.001)." (PMID 31450620, 2019). "Furthermore, we demonstrated that the enhanced expression of Beclin 1 and LC3 in KFs was reduced by glycyrrhizin treatment, while apoptosis was enhanced in keloids." (PMID 31450620, 2019).
Listeria infection (2 papers, 2019 to 2025). "Becn1 in mice was also found to maintain the quiescence of tissue-resident macrophages to resist Listeria monocytogenes infection." (PMID 39589832, 2025). "Previous work has reported modification of the autophagy regulator Beclin-1 by ISGylation57, however, this specific modification does not appear to occur during Listeria infection." (PMID 31772204, 2019).
mastitis (2 papers, 2024 to 2026). Inflammation of breast tissue during lactation or postpartum due to an obstructed duct or infection. "Moreover, Western blotting assay also manifested remarkably decreased ZO-1, claudin-1 and occludin expressions in subclinical mastitis by contrast with those in the healthy ones, while the opposite trends in beclin-1 and LC3 expressions were obtained." (PMID 39765775, 2024). "Tissue immunofluorescence analysis showed that when compared with the healthy mammary gland, the mammary glands with subclinical mastitis exhibited notably lowered ZO-1, occludin and claudin-1 expressions, as well as clearly elevated LC3 plus beclin-1 expressions at the protein level." (PMID 39765775, 2024).
metastatic carcinoma (2 papers, 2014 to 2025). A carcinoma which has spread from the original site of growth to another anatomic site. "Our findings revealed that the expression levels of Beclin-1, LC3B, and ATG7 proteins in epithelial cells progressively increased from adjacent normal tissues to primary tumors, and were further elevated in metastatic cancers (all P < 0.001)." (PMID 39922805, 2025). "Immunohistochemically, primary carcinoma showed stronger Beclin 1 expression than NNM and metastatic carcinoma in the liver (p < 0.05)." (PMID 25196438, 2014).
myeloid leukemia (2 papers, 2008 to 2023). A clonal proliferation of myeloid cells and their precursors in the bone marrow, peripheral blood, and spleen. "Expression of the genes beclin-1 and ube2b was found to be decreased in myeloid leukemia cell lines and primary AML cells in which CREB was downregulated." (PMID 18801183, 2008).
neuropathy (2 papers, 2018 to 2025). A disorder affecting the nervous system that manifests with pain, tingling, numbness, and/or muscle weakness. "By knocking out Beclin 1 in SCs here a novel mouse model (Becn1 cKO) is generated, developing a severe and progressive neuropathy, accompanied by involuntary tremors, body weight loss, and premature death." (PMID 39680476, 2025).
ocular toxoplasmosis (2 papers, 2010 to 2025). Ocular toxoplasmosis is an infection in the eye caused by the parasite, Toxoplasm a gondii. "Moreover, T. gondii-infected CD40 deficient mice had lower Beclin 1 levels in their brain microglia/macrophages and Beclin 1-deficient mice were susceptible to cerebral and ocular toxoplasmosis." (PMID 21217818, 2010). "Moreover, mice with diminished expression of Beclin 1 and mice with inactivation of Atg7 in microglia/macrophages are susceptible to cerebral and ocular toxoplasmosis despite upregulation of IFN-γ, TNF-α and NOS2 as well as the induction of T cell-mediated immunity." (PMID 21217818, 2010). "We used mice with heterozygous deletion of Beclin 1 (Becn1+/− mice) to begin to test the in vivo relevance of the autophagic pathway in protection against cerebral and ocular toxoplasmosis." (PMID 21217818, 2010). "Autophagy-deficient Beclin 1+/− mice, mice with deficiency of the autophagy protein Atg7 targeted to microglia/macrophages as well as CD40−/− mice exhibited impaired killing of T. gondii and were susceptible to cerebral and ocular toxoplasmosis." (PMID 21217818, 2010).
Peritoneal Fibrosis (2 papers, 2017 to 2022). Disorder characterized by a wide range of structural changes in PERITONEUM, resulting from fibrogenic or inflammatory processes. "In conclusion, LY294002 and rapamycin promoted expression of autophagy-related proteins LC3-II/I, p62, and beclin-1 through regulating PI3K/AKT/mTOR signalling pathway to resist the process of peritoneal fibrosis in vitro and in vivo." (PMID 35309056, 2022).
pneumonia (2 papers, 2021 to 2024). An acute, acute and chronic, or chronic inflammation focally or diffusely affecting the lung parenchyma, caused by an infection in one or both of the lungs (by bacteria, viruses, fungi, or mycoplasma.). "In addition, the findings of the present investigation determined that in the pneumonia model of animals, the level of mTOR in lung tissue was significantly increased, while a considerable decrease in the levels of LC3 and BECN1 was induced after pneumonia." (PMID 38580929, 2024).
pterygium (2 papers, 2017 to 2025). A wedge-shaped fibrovascular lesion arising from the bulbar conjunctiva and extending to the cornea. "Activated autophagy with increased Beclin 1 expression was observed when Bcl-2 was silenced by siRNA in cultured pterygium epithelial cells." (PMID 28779179, 2017). "mTORC1 activation inhibits apoptosis in pterygium by regulating Beclin 1-dependent autophagy via targeting Bcl-2." (PMID 28779179, 2017). "Our results demonstrated that the negative effect of activated mTORC1 in the apoptosis of pterygium epithelial cells occurs, at least in part, through the inhibition of Beclin 1-dependent autophagy by targeting Bcl-2." (PMID 28779179, 2017).